LRRC17 (leucine rich repeat containing 17)
Description:
Involved in bone homeostasis. Acts as a negative regulator of RANKL-induced osteoclast precursor differentiation from bone marrow precursors (By similarity).
Synonyms: P37NB; H_RG318M05.3
Tractability: Small molecule: it belongs to a druggable protein family. Antibody: UniProt places it where antibodies can reach, with medium confidence; UniProt predicts a signal peptide or a membrane-spanning region; its Gene Ontology location is reachable by antibodies, with medium confidence.
Gene: Protein-coding gene on chromosome 7 (102,912,941 to 102,945,111, forward strand). Ensembl gene ENSG00000128606.
Subcellular location: Secreted, extracellular space
Subcellular location (Human Protein Atlas): Vesicles; Cytokinetic bridge; Predicted to be secreted
Gene Ontology:
Molecular function: signaling receptor activity
Biological process: bone marrow development; negative regulation of osteoclast differentiation; osteoblast differentiation; osteoblast proliferation
Cellular component: extracellular region; plasma membrane
Genetic constraint (gnomAD): Loss-of-function variants: 33 observed, 42.55 expected, observed/expected ratio (o/e) 0.78, 90% interval 0.59 to 1.04. The upper end of that interval is the gene's LOEUF score, 1.04, which puts it in group 4 of 6, group 1 being the genes least tolerant of losing a copy. Missense variants: 491 observed, 548.03 expected, observed/expected ratio (o/e) 0.9, 90% interval 0.83 to 0.96. Synonymous variants: 192 observed, 209.2 expected, observed/expected ratio (o/e) 0.92, 90% interval 0.81 to 1.03.
Homologues: Orthologues: chimpanzee LRRC17 (99% identical), macaque LRRC17 (99% identical), pig LRRC17 (91% identical), rabbit LRRC17 (90% identical), guinea pig LRRC17 (89% identical), mouse Lrrc17 (88% identical), rat Lrrc17 (87% identical), dog LRRC17 (86% identical), tropical clawed frog lrrc17 (61% identical), zebrafish lrrc17 (49% identical). Paralogues in human: TLR8 (22% identical), TLR3 (20% identical), TLR7 (20% identical), TLR4 (19% identical), LRRC32 (18% identical), RXFP1 (17% identical), RXFP2 (17% identical), TLR6 (17% identical), TLR2 (16% identical), TLR5 (16% identical), TLR1 (16% identical), NRROS (15% identical), and 10 more.
Diseases named in the same sentence as LRRC17 in open-access papers:
LRRC17 is named in the same sentence as 10 diseases in open-access papers, as found by Europe PMC text mining. Sharing a sentence is not in itself a finding about the gene and the disease. The quoted sentences say what the papers report.
osteoporosis (4 papers, 2022 to 2024). A condition of reduced bone mass, with decreased cortical thickness and a decrease in the number and size of the trabeculae of cancellous bone (but normal chemical composition), resulting in increased fracture incidence. "LRRC17 was reported to regulate bone metabolism through the Wnt signalling pathway to prevent osteoporosis." (PMID 38332532, 2024). "When the LRRC17 gene is knocked out, aging bone marrow stromal stem cells can recover their vitality, which has the effect of treating osteoporosis." (PMID 36107565, 2022). "The downregulation of the LRRC17 protein in OA synovial fluid may reflect an affected pathway that is shared by the pathology of osteoporosis." (PMID 36983761, 2023).
aneurysm (1 paper, 2019). Bulging or ballooning in an area of an artery secondary to arterial wall weakening. "We selected and validated the genes randomly (Lrrc17, Gxylt2, Mfsd2a, Scube and Ank2) and based on their role in aneurysms (Mmp12, Spp1, Ctss) or cardiovascular complications (Mfap4, Igfbp2) or inflammatory signalling pathways (Ccls and Ccrs)." (PMID 30677223, 2019).
breast carcinoma (1 paper, 2023). "Importantly, increases in COL8A1, BGN, COL11A1, POSTN, MMP11 and SORCS2 and decreased LTBP4, PCOLCE2, LRRC17 and SDK1 have been identified in CAS and CAFs from human breast cancer and are consistently perturbed in stroma of canine and human mammary cancer." (PMID 37391533, 2023).
neuroblastoma (1 paper, 2016). Neuroblastoma (NB) is the most common solid, extracranial childhood tumor. "Additional five mutated genes (LRRC17, PXDN, FZD1, ARHGEF10L, ATRX) were highly expressed in neuroblastoma and involved in cancer progression." (PMID 27009842, 2016). "Other five genes (LRRC17, PXDN, FZD1, ARHGEF10L, ATRX) resulted to be expressed in neuroblastoma and involved in cell migration and invasion." (PMID 27009842, 2016).
ovarian carcinoma (1 paper, 2022). A malignant neoplasm originating from the surface ovarian epithelium.
cancer (3 papers, 2016 to 2022). A tumor composed of atypical neoplastic, often pleomorphic cells that invade other tissues. "Third, previous studies of LRRC17, ZHX3, LYPD6B, KIAA2022, and CMBL in cancer still remain paucity despite the importance of them." (PMID 31856408, 2020).
tumor (3 papers, 2022 to 2024). "For instance, our study showed that the overexpression of NUAK1, LRRC17, FOXM1, and CDC20 as well as the downregulation of FLRT2 are associated with DNA repair pathway as well as tumor invasion pathways." (PMID 39149564, 2024). "The results showed that compared with HSKMC, PODXL2, LRRC17, GABRA3, SCUBE3, and RFLNB were highly expressed in tumor cells, while IGHG2 and HLF were low expressed." (PMID 36155774, 2022). "So far, no studies have shown that these seven genes (IGHG2, PODXL2, LRRC17, GABRA3, SCUBE3, HLF and RFLNB) are directly related to pyroptosis in tumor cells." (PMID 36155774, 2022).
hematological malignancies (1 paper, 2020). "Among the identified seven genes (LRRC17, ZHX3, CD38, AKR1B10, LYPD6B, KIAA2022, and CMBL) in our study, CD38 was well known about its correlation with hematological malignancies." (PMID 31856408, 2020).
LRRC17 also shares sentences with these, for which no sentence is quoted: mammary cancer (1 paper); sarcoma (1).